MYD88 (MYD88 innate immune signal transduction adaptor)
Diseases named in the same sentence as MYD88 in open-access papers (continued):
Sharing a sentence is not in itself a finding about the gene and the disease.
infection (continued). "MyD88/Trif double-deficient mice consequently lacked protection against epithelial superinfection, with no protective effect of wild-type C. rodentium pre-infection over the control pre-treatment with a Δler mutant." (PMID 28662171, 2017). "MyD88-mediated signaling downstream of Toll-like receptors and the IL-1 receptor family is critically involved in the induction of protective host responses upon infections." (PMID 28520792, 2017). "Thus, mucosal innate immune activation through MyD88/Trif-TLR-signaling determines severity of ongoing A/E pathogenesis in an early phase of infection." (PMID 28662171, 2017). "Adult C57BL/6 mice deficient for toll-like receptor 4 (TLR4) or myeloid differentiation factor 88 (MyD88), μMT mice devoid of B cells as well as C57BL/6 mice deficient for the decay-accelerating factor (DAF)-1ko, were shown to die after infection with L. interrogans serovar Copenhageni." (PMID 28270811, 2017). "Induction of autophagy by HSV-1 in THP-1 cells involved MyD88, since infection of MyD88-deficient cells does not trigger autophagy." (PMID 29207540, 2017). "In contrast, only about 70% of MyD88-/- mice succumbed to infection by that time point." (PMID 29049365, 2017). "Interestingly, infection of MyD88-/- mice with the IκBαM-transgenic virus led to an even greater defect in latency establishment, suggesting that MyD88 has additional NF-κB subunit-independent effects on the latency reservoir." (PMID 27582728, 2016). "Infection of mixed MyD88-/- and WT bone marrow chimeras revealed a defect in latency establishment in the MyD88-/- B cells that was accompanied by a decrease in activation, germinal center participation, and Ig isotype class switching as compared to WT B cells." (PMID 27582728, 2016). "If Legionella-induced MTOR activity interferes with a host cell death response, it would be predicted that in the presence of TLR-signaling the host Akt/MTOR-ubiquitination pathway will phenocopy the effect of the pharmacological inhibitors in Myd88-/- BMMs infections." (PMID 27942021, 2016). "We elicited LCMV primed T cells in congenic wild type mice, purified CD4+ T cells on day 8 post-infection at the peak of T cell expansion, and adoptively transferred the cells into naïve Myd88-/-, IL-1R-/-, TLR2, 3, 4, 7, 9-/-, TLR3, 7, 9-/- and wild type mice." (PMID 27542117, 2016). "to 48 h.p.i., albeit at much higher levels for the qRT-PCR data, OAS1 and MYD88 exhibited highly similar upward trend of upregulated expression levels for both data sets across all infection time-points, although at much enhanced levels for the qRT-PCR data (respectively)." (PMID 26892458, 2016). "In addition, the common TLR adaptor protein myeloid differentiation primary response gene 88 (MyD88) is absolutely required for the control of the infection." (PMID 27309732, 2016). "We established alternate routes of infection and analyzed preferred target cells for Waddlia infection in vivo and have taken initial steps to elucidate molecular mechanisms regulating infection, including the impact of MyD88 signaling in knockdown larvae." (PMID 27917158, 2016). "First, during a complex polymicrobial infection, MyD88-independent signals, such as tumor necrosis factor α, may be sufficient to stimulate neurovascular inflammation and BBB breakdown." (PMID 26790027, 2016). "MyD88 flies infected with the ∆HTL strain succumbed faster to the infection (time for death of 50% of the flies [LT50] was about 110 hours), while flies infected with the yps11 strain were killed slower (LT50 about 130 hours), but nevertheless faster than vpk1 flies (LT50 about 180 hours)." (PMID 27767081, 2016). "Consistent with the initial ISG screen, a dose-response to infection revealed that MYD88 and UNC93B1 reduced Lm infectivity (defined as the MOI of Lm required to achieve 50% cellular infection during the course of 8 hours) by 9.7-fold and 5.7-fold compared to firefly luciferase control." (PMID 28002492, 2016).
infection (continued). "Importantly, relative to WT mice, Myd88-/- mice showed a markedly attenuated cytokine and chemokine response at 6 hours after infection with D39 (P<0.005 in all cases)." (PMID 25700108, 2015). "Increased CFUs in DKO and MyD88−/− mice early after infection could be due to differences in recruitment of innate cells with anti-bacterial function, such as neutrophils and inflammatory monocytes." (PMID 26441965, 2015). "By generating mice deficient in both MyD88 and CD40, we set out to elucidate whether synergy between MyD88 and CD40 influences the anti-bacterial immune response during infection with a live pathogen." (PMID 26441965, 2015). "However, the role of T cell intrinsic signals including MyD88 and upstream TLRs and IL-1R family members for Tc17 (and Tc1) responses during immunity to infection has been less clear." (PMID 26367276, 2015). "Whereas Myd88-/- mice infected with D39 displayed a modestly impaired bacterial clearance, these knock-out mice showed 105-fold higher bacterial burdens in their lungs 24 hours after infection with D39Δcps as compared to WT mice." (PMID 25700108, 2015). "The mortality defect observed in MyD88(−/−) mice can be significantly ameliorated by administration of a single dose of recombinant CXCL1 at the onset of infection, consistent with the notion that MyD88-coupled signals act to orchestrate neutrophil recruitment." (PMID 25621893, 2015). "It furthermore indicates that MyD88-dependent TLR signalling is necessary to achieve normal levels of IE-gene expression within the first 6 h post infection and shows that the boost in viral enhancer activity can be triggered by both, MyD88-dependent and -independent TLR signalling." (PMID 25856589, 2015). "Therefore to further test and validate the results of the transient siRNA knockdowns in MEFs in our experimental BMDM system, we next treated BMDMs with a MyD88-inhibitor peptide at increasing concentrations before infection." (PMID 25856589, 2015). "While the present finding of enhanced bacterial growth of D39 in Myd88-/- mice is in accordance with earlier results after infection with serotype 4 or 19F S. pneumoniae, we demonstrate that MyD88 plays a more important role in limiting pneumococcal growth after infection with D39Δcps." (PMID 25700108, 2015). "To examine whether the TLR pathway is also involved in activating NF-κB and releasing cytokines in the early stages of infection, we generated MyD88-knockdown cell lines based on a Tet-on system." (PMID 25761061, 2015). "In the case of wild type macrophages, Dot+ and Δ5 infections induced comparable levels of MyD88-dependent cytokine transcription and translation, and this could be observed in macrophages that were sorted by flow cytometry, as well." (PMID 25058342, 2014). "Given that previous reports have demonstrated that MyD88−/− mice following infection with different Leishmania species have an impaired ability to produce IL-12, we tested whether this could also be the case in LRV harboring L. guyanensis infected mice." (PMID 24801628, 2014). "Increased mucosal damage and inflammation in MyD88-deficient mice were attributed to a lack of neutrophil recruitment to the site of infection." (PMID 24995345, 2014). "In contrast, MyD88−/−TRIF−/− mice were similar to their MyD88−/− counterparts, with reduced H. polygyrus adult worm survival and egg production, compared with wild-type mice, by day 28 post infection, confirming that MyD88 is a key adapter protein in host susceptibility to H. polygyrus." (PMID 25114104, 2014). "We hypothesize that the lack or inconsistent impact of TLR7/MyD88 on acute FV infection may reflect the fact that the neutralizing antibody responses do not play a significant role in inhibiting FV at the earliest infection time points." (PMID 25539593, 2014). "Indeed, MyD88-deficient mice lack the production of neutrophil chemokines (CXCL1, CXCL2) at the infection site." (PMID 25084278, 2014).
infection (continued). "MyD88 is crucial for Th1 cell responses against primary IVA infection." (PMID 24527057, 2014). "Although mice lacking MyD88 cannot survive infection with WT Lm, MyD88/STING-deficient mice died earlier than MyD88-deficient mice (data not shown)." (PMID 24391507, 2014). "In our hands, LVS infection was not affected by MyD88 deficiency as compared to Thp-1-xBlue cell controls." (PMID 25295729, 2014). "Notably, at later time points (starting 2 weeks post infection) viral loads were increased in MyD88−/− mice, consistent with a weakened humoral immune response." (PMID 25539593, 2014). "Our experimental data clearly supported a role for the innate immune system and MyD88-dependent signaling pathways in the development of resistance to infection with L. guyanensis, and also implied a partial role for the MyD88 dependent, TLR9 signaling pathway." (PMID 24801628, 2014). "Our results showed that hMPV infection of moDCs significantly enhanced MyD88 expression." (PMID 24618691, 2014). "Recent research on the molecular signaling pathways triggered during the infection of T. gondii have demonstrated that the adaptor molecule MyD88, recruited after Toll-like receptor (TLR) activation by parasite molecules, is required for the establishment of this protective immune response." (PMID 23374751, 2013). "After infection, c-Jun and c-Fos bind to the AP-1 binding sites in the miR-21 promoter and evoke AP-1 mediated miR-21 induction, leading to the silencing of MyD88 and IRAK1, which play a major role in the initiation of the antiviral response in host cells and increased virus production." (PMID 23633945, 2013). "Myd88/Trif-null mice exhibited a pattern of secretion of IFN-γ as well as IFN-γ induced chemokines mostly identical to C57BL/6 controls with a peak of CCL2 at day 4 of infection." (PMID 23762028, 2013). "TLR4 first recruits TRIAP and MyD88 to the site of infection." (PMID 23799152, 2013). "Indeed, studies in TLR2-deficient mice suggest a phenotype intermediate between MyD88-deficient and control mice, indicating that TLR2 participates in the control of infection." (PMID 23940747, 2013). "Moreover, mice deficient of or with modified versions of TLR2, TIRAP, MyD88 and/or IRAK4 were more susceptible to infection with Staph. aureus, En. faecium and/or Strep. pneumoniae infection." (PMID 23873783, 2013). "Therefore, it is likely that both the MyD88-Traf6-dependent pathway and parallel MyD88-independent signalling routes contribute to the infection-induced expression of miR-146." (PMID 24112639, 2013). "MyD88−/− mice infected with the gastrointestinal nematode Trichuris muris also display elevated Th2 responses relative to their WT counterparts resulting in enhanced resistance to infection." (PMID 22884360, 2013). "Similarly, microarray-based analysis of the murine bone marrow-derived macrophage transcriptome following infection with virulent M. tuberculosis in vitro was also shown to induce MyD88-independent signalling pathways, possibly involving TLR2." (PMID 22384131, 2012). "It is possible that Brucella inhibit IgA class switch recombination or secretion via MyD88 by an unknown mechanism in order to initiate infection through mucosal surfaces." (PMID 22973560, 2012). "In particular, bacterial burdens on catheters and surrounding tissues were significantly elevated in MyD88 KO mice during acute infection, which correlated with a failure in infection containment, as evidenced by increased dissemination to the kidney and heart at days 3 and 7 post-infection." (PMID 22879997, 2012). "Although IL-1β is the major cytokine that induces IL-1R/MyD88-dependent neutrophil recruitment during a S. aureus skin infection, the source and kinetics of IL-1β production during an infection in vivo has remained unknown." (PMID 23209417, 2012). "Contrary to Myd88−/−, the Myd88−/−Trif−/− double deficient mice were not able to control parasite levels in the bloodstream and die at an earlier time point after infection." (PMID 22496959, 2012).
infection (continued). "Specifically, bacterial burdens were significantly increased on indwelling catheters and surrounding tissues of MyD88 knockout (KO) compared to wild type (WT) mice during early stages of infection, which coincided with enhanced dissemination to the heart and kidney." (PMID 22879997, 2012). "Herein, we tested whether 2 important mediators of inflammation during T. cruzi experimental infection (MyD88, IL-12 and IFN type I) could account for this pattern of CD95 expression on specific CD8+ T cells." (PMID 22615561, 2012). "Furthermore, it is evident that SE infection of the line A heterophils induce the activation of both a MyD88-dependent and a TRIF-dependent TLR signaling pathways." (PMID 22783275, 2012). "The differential impact of MyD88 signaling on chemokine expression at 12 versus 24 h post-infection led us to examine whether these changes correlated with alterations in peripheral immune cell influx." (PMID 21496301, 2011). "Bacterial burdens were similar between MyD88 KO and WT mice at 12 h post-infection." (PMID 21496301, 2011). "Since our data reveal that MyD88 plays a critical role in the induction of IFN-β, it is conceivable that the decreased IFN-β production contributed to the high susceptibility of MyD88-deficient mice to the infection." (PMID 21625574, 2011). "Interestingly, neutrophil and macrophage influx remained significantly lower in MyD88 KO compared to WT animals at 24 h post-infection, which contrasted with the heightened chemokine expression observed at this interval." (PMID 21496301, 2011). "Interestingly, expression of miR-155, miR-125a-3p, miR-146a and miR-149 was significantly reduced in MyD88−/− compared to WT BMDMs upon infection with Δhly-Lm (respectively)." (PMID 22114673, 2011). "We found that the bba64 mutant did not establish an infection in the MyD88-deficient mice via nymphal infestation, unlike the WT and complement isolates." (PMID 21559293, 2011). "Indeed, MyD88 deficiency resulted in complete abrogation of IFNγ production by CD4+ T-cells and an inability to control infection." (PMID 21253574, 2011). "Interestingly, MyD88-independent pathways were triggered with a delayed kinetics (i.e. 24 h), likely representing a compensatory mechanism in an attempt to contain infection." (PMID 21496301, 2011). "The percentage of microglia recovered following C. koseri infection was also significantly attenuated in MyD88 KO mice, which may be a consequence of the extensive necrosis that accompanied infection in these animals." (PMID 21496301, 2011). "A study in Myd88-/- mice infected with L. major has highlighted the importance of TLRs, IL-1 and/or IL-18 in the induction of IL-12 and the generation of Th1 responses; MyD88 deficiency also resulted in complete abrogation of IFNγ production by CD4+ T cells and an inability to control infection." (PMID 21253574, 2011). "Finally, we examined TLR9 knockout mice using this same infection model to define its specific contribution towards MyD88-dependent pathogenesis in a unified manner." (PMID 22039448, 2011). "The cecum from TLR4−/− and MyD88−/− had marked inflammatory cell infiltrates with oedema and epithelial disruption on days 3 and 7 post infection, that was significantly (p<0.05−0.01) greater than the mild inflammation in the cecum of infected wild-type, TLR2−/− or TRIF−/− mice." (PMID 21738466, 2011). "In this regard, although IFN-γ and MyD88 signaling were documented to contribute to TNF and NO production in T. brucei infected mice, it is unknown whether IFN-γ and/or MyD88 signaling are involved in Tip-DC differentiation during infection." (PMID 20714353, 2010). "In previous studies, our laboratory demonstrated a link between an impaired early neutrophil influx (at 24 hours post infection) and a subsequently increased bacterial growth in MyD88 KO and urokinase type plasminogen activator receptor KO mice infected with B. pseudomallei." (PMID 20824216, 2010).
infection (continued). "Therefore, the MyD88 pathway is required for innate immunity to control infection with Toxoplasma, even though adaptive immunity against the pathogen can be triggered without the need for this TLR adaptor molecule." (PMID 20442858, 2010). "Analysis of the numbers of cell-associated Mp by real-time PCR at 8 h after infection showed that approximately 10% of the original inoculum remained in the WT BMM culture, compared to approximately 80% of the original inoculum in the MyD88−/− BMM culture." (PMID 21203444, 2010). "However, while the percentage of IFN-γ producing CD4 T cells increased 10 days after infection in wild-type mice, the increase of IFN-γ producing cells was considerably less in MyD88-deficient mice." (PMID 20668698, 2010). "Furthermore, the number of CD4−CD8α− DCs per spleen was unchanged upon infection in wild type and MyD88−/− mice, but was significantly increased in TLR2−/−xTLR4−/− and TRIF−/− mice." (PMID 21124820, 2010). "Together, these results clearly indicate that deficiency in TLR2, TLR4, TLR9 or even MyD88 expression does not impair CD8+ T cell effector responses during infection with T. cruzi." (PMID 20442858, 2010). "Recently, Toll-like receptors (TLRs) have been shown to recognize T. cruzi molecules and mice lacking MyD88, the key adaptor for most TLRs, are extremely susceptible to infection." (PMID 20442858, 2010). "Here, we demonstrate that the early immune response to CB4 is solely dependent on TLR3 signaling as infection of TLR3 deficient but not MyD88 deficient mice had fatal consequences." (PMID 19122812, 2009). "In addition, infection can activate caspase 8 directly through the innate immune system via toll-like receptors (TLRs) and the adaptor molecule MyD88." (PMID 20069051, 2009). "Myd88-deficient mice sustain high titers of F-MLV for several months post-infection, indicating that the response is not simply delayed." (PMID 19214214, 2009). "Further evidence arises also for MyD88 by differential expression in mouse strains of divergent resistance post infection with Trypanosoma congolense which is of particular interest because of the ambiguous involvement of MyD88 into the control of protozoan infections." (PMID 19432955, 2009). "Remarkably, MyD88 KO and WT mice displayed similar lung pathology at 72 hours after infection." (PMID 18946505, 2008). "MyD88−/− mice infected with rMA15 have significantly higher and prolonged virus titers in the lung, exhibit a severe delay in host immune and inflammatory responses, including monocyte/macrophage recruitment to the lung, and ultimately succumb to infection." (PMID 19079579, 2008). "TLRs are required for control of L. pneumophila infection in vivo, as mice lacking TLR2 are more susceptible to infection, and Myd88−/− mice have a profound defect in controlling L. pneumophila infection." (PMID 19043549, 2008). "Thus, UL88 appears to modulate MyD88 at the protein level following a low MOI infection." (PMID 40638072, 2025). "The Toll-like receptor (TLR)-mediated MyD88/nuclear factor kappa B (NF-κB) signaling pathway is a canonical inflammatory signaling pathway in organisms, playing a crucial role in immune defense and inflammation regulation during pathogen infection or tissue damage." (PMID 41017465, 2025). "As we observed that MyD88 is only slightly upregulated at 4 h post-infection in the DF-1 cell but is strongly upregulated in the DSK cells, we may speculate that the mechanism by which MyD88 is involved in the innate immunity is not mediated by the transcriptional regulation of the encoding gene." (PMID 40981440, 2025). "Here we show that mosquitoes knocked down for Myd88 had significantly higher infection and transmission rates when exposed to MAYV‐infected obese mice compared to the GFP knocked‐down group, underscoring the importance of the Toll pathway in controlling alphavirus infection in mosquitoes." (PMID 39466902, 2024).